EIF5B (eukaryotic translation initiation factor 5B)
Diseases named in the same sentence as EIF5B in open-access papers (continued):
Sharing a sentence is not in itself a finding about the gene and the disease.
tumor (10 papers, 2016 to 2024). "In general, the number of ceRNAs involved in this interaction tends to increase, while the expression of EIF5B, which is associated with poor prognosis, is slightly increased in tumor tissue." (PMID 38627780, 2024). "We next analyzed the effects of EIF5B downregulation on the CSC phenotype of HCC cells using the tumor sphere formation assay." (PMID 37305324, 2022). "As expected, overexpression of EIF5B increased colony formation, cell migration and tumor sphere formation ability." (PMID 37305324, 2022). "The subunits involved in the translational machinery of OC in tumour tissue or cell lines has been reported for eIF6, eIF5A, eIF5B, eEF1 and eIF2α." (PMID 35718769, 2022). "The effect of peripheral blood mononuclear cells (PBMCs) on tumor cells was observed, and the interaction between eIF5B and Wig1 was revealed by co-immunoprecipitation (CoIP) assay." (PMID 34525951, 2021). "PC-3 cells transfected with sh-eIF5B or sh-control were used for tumor transplantation experiments in vivo." (PMID 34525951, 2021). "Our results suggest that inhibition of eIF5B can induce strong anti-tumor immune effects by down-regulating PD-L1." (PMID 34525951, 2021). "In fact, high eIF5B levels were associated with poor prognosis for HCC patients, while low eIF5B levels resulted in smaller tumor sizes, lower vascular invasions, and better survival rates." (PMID 34512736, 2021). "We then examined eIF5B protein expression in 6 paired HCC tumor and normal primary tissues and found that eIF5B expression is higher in tumor tissues than in normal primary tissues." (PMID 27694689, 2016). "All of the functional experiments also confirm the function of eIF5B as a tumor driver in HCC progression." (PMID 27694689, 2016). "To further study eIF5B expression in tumor tissues, we examined a panel of paired tumor and normal primary tissue specimens that were collected from patients with HCC (n=100)." (PMID 27694689, 2016). "As assessed by measurements of tumor volume and mass, eIF5B knockdown significantly decreased overall tumor growth." (PMID 27694689, 2016). "The staining density of the eIF5B protein in the tumor group was stronger than that observed in the peri-tumor group (P<0.001)." (PMID 27694689, 2016). "EIF5B down-regulation significantly impaired tumor sphere formation ability of the HCC cells." (PMID 37305324, 2022). "We found that the tumor volumes and weights in the sh-control + IgG control group were the greatest, followed by the sh-control + anti-PD-L1 group, the sh-eIF5B + IgG control group, and the sh-eIF5B + anti-PD-L1 group decreased; in addition, the differences among groups were significant." (PMID 34525951, 2021). "Finally, the effects of interference with eIF5B expression on the growth, morphology, and immunity of the tumor, as well as PD-L1 expression in the tumor, were verified by tumor xenograft assays in vivo." (PMID 34525951, 2021). "In addition, we demonstrated that both the interference with eIF5B expression or the administration of PD-L1 antibodies can inhibit tumor growth in animals." (PMID 34525951, 2021). "Moreover, interference with eIF5B expression can inhibit tumor growth, destroy tumor morphology, and suppress the proliferation of tumor cells." (PMID 34525951, 2021). "We found that the eIF5B knockdown obviously decreased subcutaneous tumor growth." (PMID 27694689, 2016). "Two cellular proliferation antigens, Ki67 and PCNA, were detected by IHC in the tumor tissues from xenografts; the expression of both of these antigens was significantly stronger in xenografts of pcshRNA-NC-transfected cells than in xenografts of pcshRNA eIF5B-transfected cells." (PMID 27694689, 2016). "The combined expression score for all tumours (EOC and BL) in eEF1A1, eIF2α, eIF5B and eIF6 nuclear expression was equal (CS = 0)." (PMID 35718769, 2022).
tumor (continued). "In the present study, we demonstrated that eIF5B expression is increased in HCC cells and tumor tissues and that this increased expression of eIF5B is associated with poor outcome in patients with HCC." (PMID 27694689, 2016). "Therefore, we sought to determine whether eIF5B knockdown could suppress tumor growth in vivo." (PMID 27694689, 2016). "The eIF5B transcript levels were much higher in the tumor tissues compared with the non-tumor tissues." (PMID 27694689, 2016).
infection (7 papers, 2011 to 2025). The state of being infected such as from the introduction of a foreign agent such as serum, vaccine, antigenic substance or organism. "This event may be associated with their lower rate of infection observed once levels of eIF5B are reduced in the cells." (PMID 30700020, 2019). "Further experiments will be required to fully understand the underlying mechanism(s) of eIF5B controlling MG1 propagation and understand the correlation between the level of available Bcl-xL protein and the rate of MG1 infection." (PMID 30700020, 2019). "Infection of enteroviruses PV and CBV begins with inhibition of host cell translation, followed by IRES-directed enterovirus protein synthesis, with eIF5B cleavage beginning at 3 hours after infection, during the attenuation of host cell protein synthesis." (PMID 28083147, 2016). "Moreover, picornaviruses have been shown to inhibit host cell translation early in infection in part by cleavage of eIF5B." (PMID 26362536, 2015). "More specifically, levels of eIF5A, eIF5B, eIF1A, eIF4H proteins, and ribosomal proteins 40S and 60S were significantly decreased in PAMs after HP-PRRSV HN07-1-infection." (PMID 35498732, 2022). "Interestingly, in the absence of infection, we observed endogenous proteolysis of proteins known to be cleaved by enteroviruses, including DDX6, HNRPM, EIF5B, G3BP1, and eIF4G1/2." (PMID 38918600, 2024).
adenocarcinoma (1 paper, 2020). A common cancer characterized by the presence of malignant glandular cells. "Using the betweenness value to rank genes in the human adenocarcinoma lymph node metastasis network, we identified EIF5B as the gene with the highest betweenness (BC = 1.0), suggesting that it has a central role in information transfer in this module." (PMID 32640634, 2020).
EIF5B also shares sentences with these, for which no sentence is quoted: lung carcinoma (2 papers); bacterial infections (1); non-small cell lung carcinoma (1); pulmonary arterial hypertension (1).